SMPDL3A (sphingomyelin phosphodiesterase acid like 3A)
Description:
Cyclic-nucleotide phosphodiesterase that acts as a negative regulator of innate immunity by mediating degradation of 2',3'-cGAMP, thereby inhibiting the cGAS-STING signaling. Specifically linearizes 2',3'-cGAMP into 2'5'-bond pGpA and further hydrolyzes pGpA to produce GpA. Also has in vitro nucleotide phosphodiesterase activity with nucleoside triphosphates, such as ATP. Has in vitro activity with p-nitrophenyl-TMP. Has lower activity with nucleoside diphosphates, and no activity with nucleoside monophosphates. Has in vitro activity with CDP-choline, giving rise to CMP and phosphocholine. Has in vitro activity with CDP-ethanolamine. Does not have sphingomyelin phosphodiesterase activity.
Synonyms: ASML3A; FLJ20177; ASM3A; yR36GH4.1
Tractability: Small molecule: a structure with a bound ligand is known. Antibody: UniProt places it where antibodies can reach, with high confidence; UniProt predicts a signal peptide or a membrane-spanning region; its Gene Ontology location is reachable by antibodies, with medium confidence. PROTAC: its protein half-life has been measured.
Gene: Protein-coding gene on chromosome 6 (122,789,049 to 122,809,720, forward strand). Ensembl gene ENSG00000172594.
Subcellular location: Secreted
Subcellular location (Human Protein Atlas): Mitochondria; Nucleoli; Nucleoplasm; Predicted to be secreted
Gene Ontology:
Molecular function: ATP hydrolysis activity; phosphoric diester hydrolase activity; protein binding; ribonucleoside triphosphate phosphatase activity; sphingomyelin phosphodiesterase activity; zinc ion binding; hydrolase activity
Biological process: negative regulation of cGAS/STING signaling pathway; nucleoside triphosphate catabolic process; sphingomyelin catabolic process
Cellular component: extracellular exosome; extracellular region
Genetic constraint (gnomAD): Loss-of-function variants: 28 observed, 29.76 expected, observed/expected ratio (o/e) 0.94, 90% interval 0.7 to 1.29. The upper end of that interval is the gene's LOEUF score, 1.29, which puts it in group 5 of 6, group 1 being the genes least tolerant of losing a copy. Missense variants: 450 observed, 494.2 expected, observed/expected ratio (o/e) 0.91, 90% interval 0.84 to 0.98. Synonymous variants: 166 observed, 177.39 expected, observed/expected ratio (o/e) 0.94, 90% interval 0.82 to 1.06.
Homologues: Orthologues: chimpanzee SMPDL3A (99% identical), macaque SMPDL3A (89% identical), pig SMPDL3A (87% identical), rabbit SMPDL3A (83% identical), dog SMPDL3A (83% identical), rat Smpdl3a (79% identical), mouse Smpdl3a (79% identical), guinea pig SMPDL3A (75% identical), tropical clawed frog smpdl3a (63% identical), zebrafish smpdl3a (52% identical), Drosophila melanogaster CG32052 (32% identical), Caenorhabditis elegans ZK856.5 (29% identical). Paralogues in human: SMPDL3B (38% identical), SMPD1 (29% identical).
Diseases named in the same sentence as SMPDL3A in open-access papers:
SMPDL3A is named in the same sentence as 18 diseases in open-access papers, as found by Europe PMC text mining. Sharing a sentence is not in itself a finding about the gene and the disease. The quoted sentences say what the papers report.
malaria (2 papers, 2021 to 2024). Malaria is a serious and sometimes fatal disease caused by a parasite that commonly infects a certain type of mosquito which feeds on humans. "We identified positive association between SMPDL3A expression in leukocytes and relative levels of AMP in the plasma during malaria." (PMID 38271704, 2024). "SMPDL3A expression was consistently up-regulated in the blood of individuals with malaria when compared with uninfected controls in diverse cohorts." (PMID 38271704, 2024). "Within the nine genes, five genes (MBP, SAMSN1, PSMF1, SLC39A8, and EIF3B) were previously found to be involved in malaria, and the remaining four genes (SMPDL3A, FABP5, SPSB3, and SHARPIN) were identified for the first time in the current study." (PMID 33942992, 2021). "Therefore, the increased SMPDL3A was possibly an indicator of eryptosis in malaria." (PMID 33942992, 2021). "Among nine key genes, four genes (SAMSN1, SLC39A8, SMPDL3A, and FABP5) were positively correlated with malaria severity and upregulated in CM." (PMID 33942992, 2021). "Of note, the relative levels of AMP were increased in the plasma and were correlated positively with SMPDL3A expression during malaria but not before infection." (PMID 38271704, 2024). "SAMSN1, SLC39A8, SMPDL3A, and FABP5 were positively correlated with malaria phenotype/severity and showed an upregulation in the CM group compared with healthy controls, while MBP, SPSB3, PSMF1, SHARPIN, EIF3B were negatively correlated with malaria severity and downregulated in the DEG." (PMID 33942992, 2021). "Moreover, SMPDL3A is a cyclic guanosine monophosphate–AMP degrading enzyme that restricts cGAS-STING signaling and may contribute to regulate type I interferon responses during malaria." (PMID 38271704, 2024).
atherosclerosis (1 paper, 2023). A disease characterized by the build-up of fatty material and calcium deposition in the arterial wall resulting in partial or complete occlusion of the arterial lumen. "Several other TG-affected genes showed weaker associations with atherosclerosis-related outcomes (ABCG1, AC004791.2, CPA3, CYP11A1, SLC12A3) or rheumatoid arthritis (GATA2, SMPDL3A) but were no longer statistically significant after correction for multiple testing (PFDR > 0.05)." (PMID 36725846, 2023).
focal segmental glomerulosclerosis (1 paper, 2014). A renal disorder characterized by sclerotic lesions in the glomeruli. "This is important as aSML3a (gene name: SMPDL3A) and aSML3b (gene name: SMPDL3B) have recently been identified as necessary for cell division and a potential target for treatment of the common kidney disease Focal Segmental Glomerulosclerosis (FSGS), respectively." (PMID 25144372, 2014).
hepatocellular carcinoma (1 paper, 2023). A malignant tumor that arises from hepatocytes. "Moreover, high expression of SMPDL3A is associated with poor prognosis in patients with hepatocellular carcinoma, and its high expression promotes the growth of hepatocellular carcinoma." (PMID 37024911, 2023).
Insulin resistance (1 paper, 2008). Increased resistance towards insulin, that is, diminished effectiveness of insulin in reducing blood glucose levels. "Also genes with a pronounced differential gene expression, of which function is not completely elucidated yet (e.g. Angptl4, H2-Q10, Oit1, Smpdl3a/b) are potential interesting signaling molecules that might contribute to development of obesity and/or insulin resistance." (PMID 18457598, 2008).
liver cancer (1 paper, 2022). An epithelial or non-epithelial malignant neoplasm that arises from the liver. "Through 180 pairs of tissue microarrays of patients with HCC, we showed that the SMPDL3A expression level was related to abnormal prothrombin, liver cirrhosis, microvascular invasion, and Barcelona clinic liver cancer (BCLC) staging." (PMID 35686107, 2022). "Data from 180 HCC patients were analyzed the relationship between the expression of SMPDL3A in liver cancer tissues and the prognosis of liver cancer patients." (PMID 35686107, 2022). "Moreover, knockout of SMPDL3A using Crispr-Cas9 genome editing technology in liver cancer cell lines significantly inhibited proliferation and migration and promoted apoptosis in cancer cells." (PMID 35686107, 2022). "SMPDL3A expression was closely related to the level of protein induced by PIVKA-II, liver cirrhosis, tumor diameter, microvascular invasion, and Barcelona clinic liver cancer staging." (PMID 35686107, 2022).
liver cirrhosis (1 paper, 2022). "The results suggest that preoperative alpha-fetoprotein level, liver cirrhosis, Child–Pugh score, portal venin tumor thrombus, microvascular invasion, and molecular level of SMPDL3A were independent risk factors affecting the overall survival of patients with HCC." (PMID 35686107, 2022). "We also analyzed the relationship between SMPDL3A and clinical indicators and showed that SMPDL3A expression was closely related to PIVKA-II level, liver cirrhosis, tumor diameter, microvascular invasion, and BCLC staging." (PMID 35686107, 2022). "Combined to the clinicopathological data of the patients, the results of t-test and chi-square test showed that SMPDL3A expression was closely related to the vitamin K absence-II (PIVKA-II) level, liver cirrhosis, tumor diameter, microvascular invasion, and BCLC staging of the patients (P < 0.05)." (PMID 35686107, 2022).
Sepsis (1 paper, 2022). Sepsis is defined as life-threatening organ dysfunction caused by a dysregulated host response to infection. "Moreover, SMPDL3A is upregulated in white blood cells of children with sepsis, in megakaryocytes in a murine model of sepsis, and in canine pyrometra." (PMID 35686107, 2022).
cancer (3 papers, 2014 to 2022). A tumor composed of atypical neoplastic, often pleomorphic cells that invade other tissues. "Our results provide a broader direction for further research of SMPDL3A in cancer." (PMID 35686107, 2022). "For the other four genes (SGCG, CCDC78, OTOP3, and SMPDL3A) in the predicted scoring model, their roles in human cancers have not yet been fully investigated." (PMID 31612869, 2019).
tumor (3 papers, 2018 to 2026). "The molecular level of SMPDL3A were independent risk factors affecting the overall survival and tumor-free survival of patients with HCC." (PMID 35686107, 2022). "The SMPDL3A level was an independent risk factor affecting postoperative tumor-free survival of patients with HCC." (PMID 35686107, 2022). "Thus, SMPDL3A is an independent risk factor that affects the tumor-free survival rate and overall survival rate of HCC patients." (PMID 35686107, 2022). "Patients with high SMPDL3A expression had significantly lower 1-, 3-, and 5-year overall survival and tumor-free survival rates than patients with low SMPDL3A expression." (PMID 35686107, 2022). "This study showed that the expression of SMPDL3A in HCC tissue differed from that in tumor-adjacent tissues." (PMID 35686107, 2022). "Xenograft tumor assays in BALB/c nude mice confirmed that SMPDL3A promoted tumor growth and in vivo." (PMID 35686107, 2022). "Patients with high-SMPDL3A expression had significantly lower tumor-free survival rate and overall survival rate than those with low-SMPDL3A expression." (PMID 35686107, 2022). "For example, MES GBMs (red arrows) were enriched for CAV1, CD44, CD63, RAB27A, SDCBP and SMPDL3A, while PN (blue arrows) tumours contained higher levels of transcripts for ANXA6, CD81, hnRNPA2B1, YBX1 (RNA binding proteins) and RAB35." (PMID 30034643, 2018). "Thus, it is of great significance to perform an in-depth study on the role and mechanism of SMPDL3A in the tumorigenesis and tumor progression of HCC." (PMID 35686107, 2022). "Moreover, the overall survival rate and tumor-free survival rate of patients with high-SMPDL3A expression were significantly lower than those with low-SMPDL3A expression." (PMID 35686107, 2022). "Moreover, the 1-, 3-, and 5-year tumor-free survival rates of the patients in the high-SMPDL3A expression group were significantly lower than those in the high-SMPDL3A expression group (P = 0.0092)." (PMID 35686107, 2022). "Thus, SMPDL3A may be a novel target for tumor-targeted therapy." (PMID 35686107, 2022). "According to the SMPDL3A expression in HCC tissues relative to the tumor-adjacent liver tissues of patients with HCC, we divided the patients into the high-SMPDL3A expression and the low-SMPDL3A expression groups." (PMID 35686107, 2022). "Our latest research showed that SMPDL3A was expressed differently in HCC tissues and tumor-adjacent liver tissues." (PMID 35686107, 2022). "Among the 180 pairs of tissue sections in this study, the difference in SMPDL3A expression in HCC tissues and the tumor-adjacent liver tissues were statistically significant (6.672 ± 3.232 vs. 5.850 ± 3.333, P = 0.0003)." (PMID 35686107, 2022). "In-depth study of the relationship between the expression of SMPDL3A and the tumorigenesis and progression of HCC showed that inhibition of SMPDL3A expression suppressed the proliferation of HCC and promoted tumor cell apoptosis." (PMID 35686107, 2022). "Immunohistochemistry was used to detect the expression of SMPDL3A on tissue chips containing 180 pairs of HCC tissues and the tumor-adjacent liver tissues." (PMID 35686107, 2022). "Subsequently, we tested the expression level of SMPDL3A using microarray to reveal the differential expression of SMPDL3A between 180 pairs of HCC tissues and the tumor-adjacent liver tissues." (PMID 35686107, 2022). "Differential expression analysis of these 27 intersecting genes in the GSE87211 dataset from GEO revealed significant expression differences between tumor and normal groups for 26 genes, with ASCL2, IFITM3, IFITM1, SMPDL3A, and SUCLG2 being the five most significantly differentially expressed." (PMID 41595533, 2026). "Expression of SMPDL3A was different in the HCC tissue and the tumor-adjacent liver tissue." (PMID 35686107, 2022).
SMPDL3A also shares sentences with these, for which no sentence is quoted: colon cancer (2 papers); infection (2); bladder cancer (1); Cirrhosis (1); colorectal cancer (1); kidney disease (1); Obesity (1); rheumatoid arthritis (1).